APP (amyloid beta precursor protein)
Diseases named in the same sentence as APP in open-access papers (continued):
Sharing a sentence is not in itself a finding about the gene and the disease.
Cognitive impairment (continued). "In order to find endocrine hormone and cytokine contributing to cognitive impairment in SAMP8 mice and APP/PS1 mice, Pearson correlation analysis was performed." (PMID 27049828, 2016). "Beginning with the APP/PS1 mouse that manifests Aβ pathology and cognitive deficits, the efficacy of this approach was demonstrated." (PMID 27129593, 2016). "Then we identified the key molecules in NIM network and cellular pathways contributing to cognitive impairment in SAMP8 and APP/PS1 mice using multiple linear regressions analysis and network fingerprint analysis." (PMID 27049828, 2016). "Expression of APP and BACE1 has been shown to be increased in neuroinflammation and to be involved in cognitive impairment." (PMID 26373740, 2015). "As the effect of different doses of caffeine on cognitive impairment and the expression of hippocampal BDNF and TrkB in PS1/APP mice have been poorly investigated, the present study was conducted." (PMID 23900282, 2013). "In 17-month-old BRI2-Aβ1-42 mice, amyloid plaque pathology as well as RIPA soluble and insoluble Aβ levels were comparable to levels found in APP CRND8 mice at the age of 4 months, when CRND8 mice showed reliable cognitive impairment in our previous studies." (PMID 23663320, 2013). "Novel object recognition was significantly reduced in 11 month old Tg APP mice and 4 month administration of JWH was able to normalize this cognitive deficit, although WIN was ineffective." (PMID 22248049, 2012). "Further studies revealed that features of ferroptosis were present in the brains of 2-month-old APP/PS1 mice, and that treatment with ferroptosis inhibitors or iron chelation significantly alleviated early pathological changes and cognitive impairment in these animals." (PMID 42123478, 2026). "Overall, APP/PS1 model demonstrates that AAVT42-mediated delivery of BDNF into the hippocampus promotes neuroprotection against Aβ-induced neurotoxicity and strengthens dendritic structure during AD pathogenesis, thus alleviating cognitive impairment." (PMID 41480410, 2026). "In APP/PS1 transgenic mice, upregulation of Notch1 and Hes1 alleviates cognitive impairment." (PMID 41596253, 2026). "Although APP expression, Aβ deposition, inflammatory markers, and autophagic flux were comparable between age groups, aged APP-expressing mice displayed cognitive impairments, hyperactivity, and motor deficits that were absent in their younger counterparts." (PMID 41495755, 2026). "However, for 3-month-old APP/PS1-mice, the age where cognitive impairments arise, GluA3 levels were decreased significantly more than GluA1 and GluA2 levels in APP/PS1-mice compared with those in the wild-type." (PMID 39779375, 2025). "Previous studies using other transgenic mouse models of AD, such as 3xTg-AD and APP/PS1 mice, have shown that general anesthetics, particularly inhalational agents such as isoflurane and sevoflurane, exacerbate cognitive impairment and promote Aβ deposition and tau phosphorylation." (PMID 40565183, 2025). "In contrast, APP/Ps1 animals of both sexes showed no significant preference for the novel object, consistent with the cognitive deficit characteristic of this model." (PMID 41300242, 2025). "On the other hand, intraperitoneal insulin does not seem to ameliorate cognitive impairment in Aß25-35-injected rats in the MWM neither in APP/PS1 in the Barnes maze." (PMID 41146261, 2025). "In our study, we also observed reduced OPA1 expression in AD patients and APP/PS1 mice and found that OPA1 activation could improve cognitive impairment in AD mice." (PMID 40354372, 2025). "Furthermore, in APP/PS1 mice, colonization with fecal bacteria from WT mice has been shown to reverse gut microbiota composition, mitigate AD pathology, and improve cognitive impairment." (PMID 39957504, 2025).
Cognitive impairment (continued). "For example, APP/PS1 double-transfer mice, many literatures show that behavioral cognitive impairment and learning and memory impairment have been detected at 10 or 12 months, or there is a significant gender difference in the transcriptome profile is already 8 months of age." (PMID 40182757, 2025). "Our results demonstrated that compared to age‐matched WT mice, 6‐month‐old and 9‐month‐old APP/PS1 mice showed cognitive decline, while 3‐month‐old APP/PS1 mice did not exhibit cognitive impairment." (PMID 41367129, 2025). "This has the effect of moving the processing of APP towards a non-pathological pathway, and alleviating cognitive impairments in APP23/PS45 transgenic mice." (PMID 39030577, 2024). "Moreover, the deletion of the NLRP3 gene in APP/PS1 mice reduces Aβ deposition and alleviates cognitive impairment." (PMID 39861665, 2024). "Moreover, in some transgenic mouse models overexpressing mutant amyloid precursor protein (APP), synaptic alteration and cognitive impairment precede amyloid plaque formation, but occur after Aβ levels start to rise steadily." (PMID 38238842, 2024). "Reductions in Aβ and APP levels have been shown to decrease excitability in mouse models, though they did not delay cognitive impairment." (PMID 38999445, 2024). "Considering the fact that APP/PS1 mice do not exhibit obvious memory impairment until 7‐month‐old, this result indicates a causal link of CaM acetylation with cognitive deficits of AD mice." (PMID 38421101, 2024). "Similarly, a decline in CBF has been repeatedly documented prior to the development of cognitive defects or amyloid plaques in multiple transgenic mouse AD models (APP23, J20, APP/PS1, 5xFAD, and Tg2576) that overexpress APP." (PMID 38434588, 2024). "Recent evidence, particularly from studies using APP/PS1 AD transgenic mouse models, suggests that long-term exposure (five weeks) to high doses (13–18 g/kg) of alcohol can induce cognitive impairments and enhance the enzymatic activity of BACE1 and γ-secretase involved in APP processing." (PMID 39056755, 2024). "Another study conducted in APP/PS1 mice found that activation of the NGF-TrkA pathway induces neurogenesis, regulates the c-Raf/ERK1-2/CREB cascade response, reduces Abeta levels, and improves cognitive impairment." (PMID 39022312, 2024). "We found that 4-month-old CKO × APP/PS1 mice exhibited substantial cognitive deficits and memory impairment, while age-matched APP/PS1 mice were not cognitively impaired." (PMID 39696695, 2024). "Similarly, the present study revealed that 4-month-old APP/PS1 mice behave spatial memory deficits, and that orchiectomy to them induces more severe cognitive deficits and synaptic protein diminution, as well as Aβ accumulation." (PMID 38752208, 2024). "This compound was tested on 3xTg-AD mice and McGill-R-Thy1-APP, attenuating cognitive deficits and mediating APP metabolism; no side effects were observed at a maximum dose of 50 mg/kg." (PMID 39057049, 2024). "However, in a different study that used APP/PS1 mice, it was reported that female mice showed cognitive impairments after 1 Gy 56Fe radiation and males after 0.10 and 1 Gy 56Fe radiation." (PMID 39273325, 2024). "A study on the Tg-APP/PS1 mouse AD model reported that hyperoxygenation increases the production of MMP-2, MMP-9, and tPA, leading to reduction of Aβ deposition in the brain and rescued cognitive impairment." (PMID 37109410, 2023). "Our results in the APP/PS1 model, where we found a beneficial effect of repeated exposure to menthol during the long process taking the development of cognitive impairment, are in line with this hypothesis." (PMID 37187754, 2023). "Some of these also provide compelling evidence that cognitive impairment following APP overexpression is largely independent of Aβ and amyloid pathology." (PMID 37750482, 2023).
Cognitive impairment (continued). "Altogether, our results have shown a positive effect of the allosteric inhibitor for c-Abl, neurotinib, over the AD pathology displayed by aged 22-month-old APP/PS1 mice, further validating c-Abl as a key player in the development of AD pathology and cognitive impairment of AD." (PMID 37358955, 2023). "By shifting APP processing to non-amyloidogenic pathways, intranasal insulin improved cognitive impairments and decreased brain Aβ levels and Aβ plaque deposition in APP/PS1 mice." (PMID 36909158, 2023). "In another APP/PS1 mouse model, the reduction in butyrate and acetate levels correlated with a poorer cognitive performance, whereas the levels of propionate were higher than in control mice and correlated with cognitive impairment." (PMID 37509487, 2023). "In some models with overexpressed APP, widespread Aβ deposition occurs but shows no subsequent cognitive deficits." (PMID 37400870, 2023). "However, when APP/PS1 mice were raised in social isolation, cognitive impairment was already evident at 3 months of age and was accompanied by a massive increase in Aβ." (PMID 37163426, 2023). "Indeed, CBZ has been reported to significantly reduce spontaneous electrographic epileptic discharges in APP/PS1 transgenic mice and to improve cognitive impairment in APP/PS1ΔE mice by reducing Aβ plaque burden." (PMID 37143270, 2023). "We validate our hypothesis in amyloidogenic APP/PS1 mice and show prolonged exposure to fingolimod alleviated synaptic plasticity and cognitive impairment in mice." (PMID 36209301, 2022). "APP/PS1 transgenic mice do not exhibit obvious cognitive impairment—in terms of either detectable brain Aβ plaques or perceptible synaptic loss—before 4 months old." (PMID 36012153, 2022). "On the other hand, increased β-cleavage of Swedish APP in the ISVAID may directly prompt L-LTP and cognitive deficits via potentiation of the BAD-Glu pathway." (PMID 36438008, 2022). "APP/PS1 double transgenic mice overexpress human amyloid precursor protein (APPsw) and mutant forms of presenilin 1 (m146L) genes, which are characterized by early amyloid deposition and early cognitive impairment and glymphatic dysfunction." (PMID 36032783, 2022). "Treatment of mouse (APP/PS1 animals) and rat (Aβ injection in the hippocampus) models of AD with these compounds decreased expression of APP, Aβ, and PDE5 and significantly attenuated AD-related cognitive deficits." (PMID 35806059, 2022). "Tetrahydroxy stilbene glycoside was shown to improve AD in APP/PS1 mice via the inhibition of GPX-related ferroptosis, while eriodictyol improves cognitive disorder in APP/PS1 mice by suppressing ferroptosis via Nrf2 activation mediated by a vitamin D receptor." (PMID 35805124, 2022). "For instance, in APP/PS1 mice, reactive hippocampal astrocytes produce and secrete the gliotransmitter GABA which activates extrasynaptic GABA receptors and inhibits synaptic function, thus triggering memory and cognitive deficits." (PMID 36131327, 2022). "The activity of SOD in the brains of APP/PS1 transgenic mice was significantly decreased, indicating decreased antioxidant capacity, and which was consistent with the clinical lesions of aging and senile patients with cognitive impairment." (PMID 35281906, 2022). "Pan-PPAR modulation could effectively protect APP/PS1 mice from amyloid deposition and cognitive deficits." (PMID 36217155, 2022). "Additionally, IFNγ produced by adoptively transferred Aβ-specific Th1 promoted increased Aβ deposition in an APP/PS1 model, alongside cognitive deficits, indicating a detrimental role for Aβ-specific Th1 cells in AD." (PMID 35872901, 2022). "Several studies have shown that Aβ-induced cognitive deficits significantly increased C99 levels compared with non-injected rats, and enhanced expression of presenilin was detected in Aβ-injected APP/PS1 Tg mice." (PMID 35053874, 2022).
Cognitive impairment (continued). "In summary, these data support that there are apoE isoform-dependent effects on hAPP/Aβ-induced behavioral alterations and cognitive impairments and Aβ pathology in mouse models containing only human APP and apoE and not the murine counterparts." (PMID 35299942, 2022). "Moreover, implantation of VEGF secreting microcapsules on the cerebral cortex of APP/PS1 mice attenuated both brain Aβ burden and cognitive impairments." (PMID 34744690, 2021). "In the present study, APP/PS1 mice were utilized as a transgenic model of AD, which exhibited progressive cognitive impairment including defective working memory, recognition memory, and spatial memory starting at 6 months of age and more severe by 8 months of age." (PMID 34916926, 2021). "Unlike previous reports, the APP/PS1 mice used in the current study did not develop cognitive deficits in the MWM even at an age of 21 months." (PMID 34209113, 2021). "To overcome potential artifacts derived from transgenes, we used a knock‐in mouse model, AppNL−F/NL−F, which accumulates Aβ plaques from 6 months of age and shows mild cognitive impairment at 18 months of age, without the overproduction of APP." (PMID 34245097, 2021). "hNSCs were transplanted intranasally to 3.5-month-old APP/PS1 transgenic mice a total of four times at a frequency of once a week, and a behavioral assessment was performed at 6.5 months when the APP/PS1 mice started to exhibit cognitive deficits." (PMID 33776747, 2021). "A prevailing hypothesis is that the production from sequential cleavage of the amyloid precursor protein (APP) by secretases and accumulation of amyloid peptides (Aβ) drives the progressive neuronal damage and cognitive impairment in AD." (PMID 34315506, 2021). "Our study showed that there were obvious cognitive impairment and Aβ plaques in APP/PS1 mice, regardless of their diet." (PMID 34168550, 2021). "Studies from Branca and colleagues also performed in APP/PS1 mice, a transgenic mice strain that produces an excess of β-amyloid plaques and cognitive impairment, showed a decrease in Nrf2 activity and significant reduction in HO-1 levels concomitantly with AD pathology and cognitive impairment." (PMID 34356302, 2021). "Moreover, a statistically significant positive correlation was found between APP mRNA levels (TOT, KPI, 770 and 751) and cognitive impairment." (PMID 34440494, 2021). "No cognitive deficits were evident in APP/PS1 mice at any age, contrary to previous reports using maze-based learning and memory tasks." (PMID 34938165, 2021). "We show that the absence of Trem2 exacerbated cognitive impairments in APP transgenic mice but not in their WT littermates." (PMID 32703241, 2020). "In vivo experiments show that 5-month-old APP/PS1 mice appeared to have impaired acquisition of spatial learning and GLTs could reduce cognitive impairment in AD mice." (PMID 32089787, 2020). "We previously reported a rhamnoside derivative named PL201A could ameliorate cognitive impairments and enhance the neural progenitor cells (NPC) proliferation and neurogenesis in APP/PS1 mice while whether it could influence Aβ pathology is unclear." (PMID 31901901, 2020). "Cognitive impairment is correlated with Aβ deposits in the PFC and HC in APP/PS1 AD mice." (PMID 32508567, 2020). "We show that the absence of Trem2 exacerbated cognitive impairments in APP transgenic mice but not in their non-APP littermates." (PMID 32703241, 2020). "The fact that brains of transgenic APP/PS1 mice contain far higher HOCl concentrations as compared to wt littermates makes it conceivable that MPO derived oxidants have the potential to contribute to induce behavioral and cognitive deficits." (PMID 32050431, 2020).
Cognitive impairment (continued). "The APP/PS1 mouse model is a double transgenic mouse model, expressing a chimeric mouse/human amyloid precursor protein, and a mutant human presenilin 1(PS1-dE9), and represents a model of familial AD with cognitive impairments, Aβ plaque deposition and synaptic abnormalities from 6 months of age." (PMID 31978506, 2020). "Interestingly, AAV-mediated SNX8 overexpression in APP/PS1 mouse brain reduced Aβ levels and reversed cognitive impairments in Y-maze tests." (PMID 31551717, 2019). "Based on the results from the behavioral tests, the 3–4-mo APP/PS1 mice suffered olfactory deficits but not cognitive impairments." (PMID 30740049, 2019). "Together, these results implicate a neuroprotective role for SNX8 in enhancing non-amyloidogenic APP trafficking, thereby suppressing Aβ accumulation and consequent cognitive impairment in AD." (PMID 31551717, 2019). "Results of the NOR test showed significant cognitive impairment in untreated APP/PS1 mice, reflected by a discrimination index (DI) of 0.198 ± 0.004 vs 0.607 ± 0.005 in WT mice (p < 0.001)." (PMID 30684442, 2019). "In addition, the 9–10-mo APP/PS1 mice suffered olfactory deficits and cognitive impairments and were considered representative of late-stage AD." (PMID 30740049, 2019). "A previous study found that APP/PS1 transgenic mice increased Aβ production and plaque formation at around 3–5 months of age; developed mild impairments of spatial memory and nesting skill at 4.5 months of age; and displayed cognitive deficits in the MWM." (PMID 29463001, 2018). "In the present study, we test the hypothesis that in 4- to 5-month-old APP/PS1 mice pathological changes to the cerebral, hepatic, splenic and renal microvasculature precede the onset of measurable cognitive impairment." (PMID 28741167, 2017). "Hence, 8-month APP/PS1 mice were administrated with diluted YXQN extract for 2 months, when the mice normally presented severe cognitive deficits and significant Aβ deposits, equivalent to moderate to severe AD patients." (PMID 28603494, 2017). "Therefore, the mechanisms of cognitive impairment in SAMP8 and APP/PS1 mice remain elusive and unclear in multi-dimension and integrated system." (PMID 27049828, 2016). "In this study, we demonstrate that Pdx1+/− mice exhibit worsening of cognitive deficits of the APP/PS1 mouse; however, the Pdx1+/− mice did not exhibit a significant deterioration in memory performance compared with that of the WT mice." (PMID 27406855, 2016). "Results showed that the NIM molecular network correlated with cognitive impairment of SAMP8 mice contained 160 nodes and 261 edges with characteristic path length 5.436 (Figure 3a2), and network of APP/PS1 mice contained 161 nodes and 293 edges with characteristic path length 4.549 (Figure 3b2)." (PMID 27049828, 2016). "This configuration, with no plaque nor tangle and with levels of APP cleavage products close to the human hippocampal condition, is sufficient to induce cognitive impairment three months after injection." (PMID 26759118, 2016). "Interestingly, this courtship preference was eliminated in aged males or males expressing APP in the courtship specific neurons driven by fru-Gal457, suggesting that expression of APP in Drosophila could mimic aging-induced choice disorder and cognitive impairment." (PMID 26597721, 2015). "Since insoluble, but not soluble, Aβ were significantly increased in middle-aged APP DSL mice, the behavioral results indicate that the cognitive deficits are associated with insoluble Aβ accumulation." (PMID 25108425, 2014). "Here we see cognitive impairment in the NOR task manifest in the APP/PS1 KI model at 15 months of age." (PMID 23705774, 2013). "The clinical relevance of our data showing a prominent increase in overall expression of EPOR in the brains of APP/PS1 mice is reflected by the studies showing increased EPOR in hippocampal and cortical astrocytes in patients with mild cognitive impairment and sporadic AD." (PMID 24124607, 2013).